CDK6 (cyclin dependent kinase 6)
Diseases named in the same sentence as CDK6 in open-access papers (continued):
Sharing a sentence is not in itself a finding about the gene and the disease.
tumor (continued). "Previous studies have elucidated that CDK6 could phosphorylate Rb protein, induces the expression of E2F1, thus inducing the transformation from G1 to S phase, promoting cell proliferation and acting as a tumor promotor in human cancer." (PMID 32310823, 2020). "Among the tumor-related genes, the top amplified genes included ERBB2 (17q21), MYC (8q24), GNAS (20q13), EGFR (7p11), ZNF217 (20q13), CCNE1(19q12), NCOA3 (20q13), and CDK6 (7q21), and the most frequently deleted genes were CDKN2A (9p21), CDKN2B (9p21), KIT (4q12), SMAD4 (18q21), and FGFR1 (8p12)." (PMID 31541076, 2019). "In addition, Fu and colleagues reported that AVA 2p treatment down-regulated other two targets of the tumor suppressor miR-129-3p: IGF2BP3 (insulin like growth factor 2 mRNA binding protein 3) and CDK6 (cyclin-dependent kinase 6), both important for G1-phase progression and G1/S-transition." (PMID 31540249, 2019). "In the sample from relapsed tumor, there exist some large signals for EGFR, CDK6, and MYC along with the widely distributed smaller signals consistent with eccDNA; therefore, we cannot rule out the possibility that HSR may co-exist with double minutes at this time." (PMID 30267146, 2019). "Furthermore, DOT1L regulates the transcription of G1 phase genes CDK6 and CCND3 through H3K79 dimethylation, thereby knocking down of DOT1L could result in G1 arrest and therefore impede the cell proliferation and tumor progression both in vitro and in vivo." (PMID 28114995, 2017). "Furthermore, DOT1L regulates the transcription of G1 phase genes CDK6 and CCND3 through H3K79 dimethylation; therefore, blocking DOT1L could result in G1 arrest and thereby impede the cell proliferation in vitro and tumor growth in vivo." (PMID 28114995, 2017). "According to public databases, our data strongly suggest CDK6, DNMT3A and DNMT3B as direct targets of miR-29a-3p: disallowed tumor-suppressive function of this miRNA may stimulate tumorigenesis by promoting cell cycle progression and altering de novo methylation of the genome." (PMID 27829219, 2016). "Interestingly, we also found these effects to be CDK4-specific and CDK6-independent, indicating that specific CDK4 pharmacological inhibitors, may prove efficient drugs for eliminating BCSCs and further preventing tumor recurrence in human TNBCs." (PMID 27759034, 2016). "DLC1 was not significantly correlated with CDK6 expression when all tumor types were considered (P = 0.0817, correlation = 0.0769) but was significantly positively correlated with CDK6 in ER-positive tumors (P = 2.18E−9, correlation = 0.2967), indicating the involvement of ER in this interaction." (PMID 25425654, 2014). "However, although higher CDK6 transcript levels in tumor cores indicated poorer survival, the correlation was not statistically significant (P = 0.0529)." (PMID 23594394, 2013). "However, in the absence of p16INK4a, CDK6 can exert its full tumor-promoting function by enhancing proliferation and stimulating angiogenesis." (PMID 23948297, 2013). "We found that Cdk4−/− tumor could grow at a similar rate as vector cells and Cdk6−/− tumor could grow to bigger size in Ifnar1−/− mice than those in WT C57 mice, suggesting the important role of IFNAR-1 in TME for the anti-tumor immunity activated in Cdk4−/− and Cdk6−/− cancer cells." (PMID 37833461, 2023).
tumor (continued). "Interestingly, CDK6, another target of the hsa-miR-29a miRNA, was found to mediate the recruitment of the transcription factors c-Jun and Sp1 to the MMP2 promoter that positively enriched the angiogenic and fibrotic tumor microenvironment, as widely observed in TNBC (ER−) patient tissues." (PMID 36834918, 2023). "Moreover, the down-regulation of miR-107 may cause cell cycle and proliferation due to the up-regulation of CDK6 (also targeted by miR-103) and CDK8 and metastasis and tumor growth because of the up-regulation of BDNF as well as indirect regulating of the P13K/AKT signaling pathway." (PMID 34635059, 2021). "However, the expression of CDK6 in the tumor can’t access without the tumor tissues." (PMID 30123094, 2018). "Unlike the already-marketed CDK4/6 anti-tumor inhibitors, BEBT-209 improves the selectivity of CDK4 over CDK6, which is expected to reduce the hematological and immunosuppressive toxicity caused by CDK6 activity inhibition." (PMID 38138549, 2023). "In comparison, nonuterine tumour samples (n=113) were positive for CDK4, CDK6, and p-Rb in 54.9%, 86.7%, and 49.6%, respectively, and expressed ≤10% p16 protein in 41.6%." (PMID 30804704, 2019). "In addition to these well-known tumor suppressors, some circRNAs could also regulate tumor growth by regulating cell cycle mediators, such as Cyclin D1, a well-known regulator of the cell cycle that promotes the transition from G1 to S phase by activating CDK4 or CDK6." (PMID 30999909, 2019). "When we analysed the site of tumor cell injection by immune-histochemical stainings 21 days after injection we found residual tumor cells that displayed no signs of proliferation upon stable shRNA knockdown for CDK4 and CDK6 when compared to controls." (PMID 30858922, 2019). "It was observed that CDK6 expression was positively correlated with MAGI2-AS3 expression in CSCC tissues, but not in non-tumor tissues." (PMID 31832086, 2019). "A negative correlation between miR-200a-3p and CDK6 transcription and a positive correlation between circ-ZEB1.33 and CDK6 transcription were found within HCC tumor tissues." (PMID 30123094, 2018). "Taken together, our findings established a tumor suppressive role for miR-1 in the progression of ccRCC by targeting CDK4, CDK6, Caprin1 and Slug and suggested miR-1 can be served as a novel potential therapeutic target for ccRCC." (PMID 26036633, 2015). "In contrast to CB42, CBP1 showed a non-significant trend toward mild tumor growth inhibition in response to the MEK-inhibitor, the CDK6-inhibitor, or the combination, reaching at most 45% TGI in the combination arm." (PMID 25162504, 2014). "In contrast to CDK6, high expression of CDK4 in p185BCR-ABL+ leukemic cells did not increase p16INK4a expression, nor was any change in tumor growth observed." (PMID 23948297, 2013). "This led us to speculate that in contrast to the in vitro situation, T cell-intrinsic CDK6 expression is not required for expansion or infiltration of CD8+ T cells during anti-viral and anti-tumor responses in vivo." (PMID 34248938, 2021). "CDK6, not CDK4, is involved in both cell cycle and tumor-promoting progression." (PMID 33597968, 2020). "Therefore, the potential nonresponder type (type 0) was defined by either p16 expression in over 10% of the tumour cells, lack of the p-Rb molecule, or the absence of both CDK4 and CDK6." (PMID 30804704, 2019). "However, end of study tumor volumes further reinforced the assessment that CBP1 had no significant response to the MEK and CDK6 inhibiting drugs." (PMID 25162504, 2014). "This may serve as a cautionary note for the identification of ALM patients who may benefit from CDK4i/6i based solely on tumor sequencing, which may prevent patients with elevated CDK4/CDK6 protein expression but no clear evidence of copy number variation in CDK4/6 pathway genes from treatment." (PMID 38066089, 2024).
tumor (continued). "Besides, the immune-histochemistry staining images illustrated that the IMP-treated tumor tissues exhibited significantly increase in PTEN- and LC3-positive cells, as well as p-AKT- and CDK6-negative cells, which were consistent with the results of external experiments." (PMID 34923996, 2021). "In the absence of CDK6, the attenuated initial ISG response is counteracted by a weakened negative feedback loop, which might contribute to the lack of obvious in vivo phenotypes upon viral or tumor challenge." (PMID 34248938, 2021). "In the absence of CDK6, attenuated negative feedback regulation might compensate for the reduced early IFN response, which could contribute to unaffected anti-viral or anti-tumor immunity in the absence of T cell-intrinsic CDK6." (PMID 34248938, 2021).
cancer (551 papers, 2004 to 2026). A tumor composed of atypical neoplastic, often pleomorphic cells that invade other tissues. "Previous studies have shown that elevated CDK2 and CDK6 expression is associated with chemoresistance and poor survival in various cancers." (PMID 41487280, 2026). "Overactivation of CDK4 and CDK6 kinases is associated with a loss of control over cell cycle regulation, contributing to cancer cell growth." (PMID 41375037, 2025). "During the process of malignant formation, the proto-oncogene cyclin D1 binds with CDK4 and CDK6, forming active complexes that promote uncontrolled cell proliferation, an underlying hallmark of cancer development." (PMID 40722732, 2025). "Recent studies have also linked CDK6 overexpression to metabolic disruptions in cancer cells via the pentose phosphate pathway." (PMID 41537091, 2025). "Loss of this miRNA leads to overexpression of CDK6 in cancer cells which promotes uncontrolled cell proliferation." (PMID 40495204, 2025). "Its target gene CDK6, a core component regulating the cell cycle, is considered a mutation target in malignant tumors." (PMID 39981435, 2025). "Often, CDK6 is hyperactivated or overexpressed, resulting in uncontrolled cell proliferation, which is why it is considered a hallmark of cancer." (PMID 38845697, 2024). "The G1 cell cycle kinase CDK6 regulates cell cycle progression and is implicated in a number of cancer types." (PMID 37966243, 2023). "Together, these data demonstrated that Cdk4 and Cdk6 deficiency in cancer cells triggered type I IFNs responses." (PMID 37833461, 2023). "The highly connected hub gene CCND1 encodes cyclin D1, which together with CDK4 and CDK6 kinases control G1 to S phase cell cycle progression and is frequently overexpressed in human cancers, promoting tumorigenesis." (PMID 37935712, 2023). "Abnormal expression of cyclins D1 and D2 in cancer cells has been discussed as being associated with resistance against CDK4/CDK6 inhibitors." (PMID 35804842, 2022). "Imbalance in the activity of CDK4 and CDK6 can induce dysregulation and uncontrolled cell division, which is a hallmark of cancers." (PMID 35459184, 2022). "A high frequency of responsive AS, mainly SE events, were induced by CDK6, CDK4, and PI3K 110α/β level changes, and these AS events finally led to the alteration of the ABCB1 expression and ABCB1-mediated MDR in cdk6 or cdk4 deficient KB-C2 cancer cells." (PMID 35459184, 2022). "Pathways leading to inhibition of cancer cell proliferation were revealed to be accompanied by CDK6 deficiency." (PMID 35459184, 2022). "Many of these significantly increased proteins encoded on autosomes, such as ERK2, FYN, and CDK6, are linked to cancer and other diseases." (PMID 33910018, 2021). "We further extended our analysis on other members of RB1 pathway, including CDKN2A (p16Ink4a), CCND1, CDK4, and CDK6, which are often mutated in different cancers." (PMID 33591981, 2021). "JMJD2B has been shown to play a role in altering the expression of many cancer associated genes including cyclin-dependent kinase 6 (CDK6), and carbonic anhydrase 9 (CA9), which can directly affect the transmembrane pH gradient." (PMID 32292719, 2020). "Despite overlapping functions in cell cycle regulation, CDK4 and CDK6 dysregulation is linked to different cancer types." (PMID 33255177, 2020). "CDK6 is directly associated with the progression of different types of cancer because the overexpression of CDK6 resulted in an uncontrolled cell cycle progression and growth." (PMID 32429317, 2020). "Another tumour suppressor gene, p16, encodes a specific inhibitor of CDK4 and CDK6 and is altered in a wide range of human cancers." (PMID 30668541, 2019). "Third, LINE-1 hypomethylation activates oncogenes (e.g., c-MET) and cell cycle-related genes (e.g., CDK6), which are associated with cancer progression." (PMID 29755690, 2018).
cancer (continued). "A further exploration of this ceRNA crosstalk module found that many protein-coding genes in it were associated with human cancers such as CDK6 and NOTCH1." (PMID 27580177, 2016). "Abnormal TDP - 43 increases in AD and loss of TDP-43 contributes to cancer via upregulation of CDK6." (PMID 27875990, 2016). "The present study provides scientific evidence supporting the potential of T. siliquosa root extract as a natural source of bioactive compounds with inhibitory effects on cyclin-dependent kinases CDK4 and CDK6, key regulators of cell cycle progression commonly implicated in various cancers." (PMID 40722732, 2025). "Notably, as associated partners of D-type cyclins, CDK4 and CDK6 exhibit multiple distinct functions in cancer." (PMID 39004679, 2024). "As such, repurposing of CDK4/CDK6 inhibitors (such as Palboclicib) to treat KSHV-associated cancers may target multiple signaling pathways which will minimize drug resistances." (PMID 38365882, 2024). "We identified three priority class A candidates—namely the SL interactors MDM2, TUBA1B (COAD/READ), and NDUFB5 (STAD) and the AL interactor CDK6 (in the pan-cancer dataset)—that encode targets of approved anticancer drugs or that are the focus of drug development efforts." (PMID 39578878, 2024). "Conversely, 11% of genes showed upregulation in cancer cell lines associated with oncogenic transformation, such as CDK6 (Log2 fold change of expression >1, adjusted p value < 0.05), as indicated by the differentiation markers upregulated by 71% in cancer lines." (PMID 39199347, 2024). "In that study, the ability of many phytochemicals other than ellagic acid (capsaicin, tocopherol, limonene, ursolic acid, rosmarinic acid, caffeic acid, and ferulic acid) to inhibit the activity of cyclin-dependent kinase 6 (CDK6), which is associated with cancer progression, was assessed." (PMID 37241819, 2023). "Furthermore, survival analysis of CDK6 in these cancer types revealed that high CDK6 expression was associated with a poorer prognosis in PC." (PMID 36457244, 2023). "If CDK6 amplification occurs, it will lead to cells susceptible to an uncontrollable proliferative division state, which plays an important role in promoting cancer development." (PMID 37360159, 2023). "CDK6 has been linked to the incidence of several cancers, according to recent studies." (PMID 35780240, 2022). "Targeting CDK6 by selonsertib could be a promising therapeutic approach for cancer and other CDK6 associated disease therapy." (PMID 35720007, 2022). "Additionally, STAT3 and CDK6 have been associated with cancer-associated fibroblast and immune cell infiltration and are considered biomarkers of poor prognosis in multiple cancers." (PMID 34572040, 2021). "Interestingly, recently deregulated CDK4/CDK6 levels were closely associated with immune suppression and control of cancer immune surveillance." (PMID 32754302, 2020). "Thus, it is noteworthy that ApoE knockout and knockdown led to decreased expression of cyclin D1 and its associated proteins CDK4 and CDK6, in urethane-induced lung tumors, lung metastases, and cancer cell lines." (PMID 31275318, 2019). "Moreover, genetic variations in CDKs have been discussed as potential risk factors conferring susceptibility to cancer whereas the influence of CDK6 polymorphisms is less reported." (PMID 30829464, 2019). "Some inhibitors of the cyclin D-associated kinases CDK4 and CDK6 may be used as potential cancer therapeutics." (PMID 27230400, 2016). "In general, cancers with p16 loss may also be sensitive to CDK4/CDK6 inhibition, with preclinical data supporting this in melanoma and lung cancer among others." (PMID 25914884, 2015). "CDK1, CDK4, and CDK6 have a diagnostic value in various cancers." (PMID 22333595, 2012). "Binding and recognition between p16INK4a and CDK4 or CDK6 proteins are mediated primarily by hydrogen-bond networks, with several of the residues that participate in these interactions being mutated in cancer." (PMID 14735200, 2004).